PLA2G6 (phospholipase A2 group VI)
Diseases named in the same sentence as PLA2G6 in open-access papers (continued):
Sharing a sentence is not in itself a finding about the gene and the disease.
injury (1 paper, 2020). Damage inflicted on the body as the direct or indirect result of an external force, with or without disruption of structural continuity. "In addition, PLA2G6 catalyzes the cleavage of phospholipid membranes, which are the most important inflammatory mediators of acute lung injury." (PMID 33195232, 2020).
liver inflammation (1 paper, 2026). "PLA2G6 inactivation specifically in hepatocytes may provide a potential therapy option to alleviate diet-induced liver inflammation." (PMID 42101094, 2026).
parkinsonian disorder (1 paper, 2012). A group of disorders which feature impaired motor control characterized by bradykinesia, MUSCLE RIGIDITY; TREMOR; and postural instability. "The clinical and neuropathological features clearly represent a link between PLA2G6 and parkinsonian disorders." (PMID 20619503, 2012).
α-synucleinopathy (1 paper, 2022). "Another study concerning PD focuses on exploring a specific subset of human iPLA2-VIA/PLA2G6 mutations that direct α-Syn aggregation and DA neurodegeneration specific for the PARK14-linked PD with α-synucleinopathy." (PMID 35269756, 2022).
neurodegenerative disease (28 papers, 2010 to 2025). A disorder of the central nervous system characterized by gradual and progressive loss of neural tissue and neurologic function. "Loss of function mutations in the gene PLA2G6 give rise to inherited neurodegenerative diseases including autosomal recessive early onset parkinsonism (PARK14)." (PMID 41404033, 2025). "Phospholipase A2-associated Neurodegeneration (PLAN) (OMIM: 610217) is a group of neurodegenerative diseases that are associated with the alterations of the PLA2G6 gene, resulting in pathological brain iron deposition (NBIA)." (PMID 34168672, 2021). "Phospholipase A2-associated Neurodegeneration (PLAN) is a group of neurodegenerative diseases associated with the alterations of PLA2G6." (PMID 34168672, 2021). "Among the target genes, which are repressed upon BMMF expression are the tumor suppressor genes E2F2 and TXNIP as well as the phospholipase PLA2G6, which is frequently mutated in neurodegenerative diseases." (PMID 29434270, 2018). "Our results provide insight into pathogenic mechanisms underlying the spectrum of neurodegenerative diseases caused by PLA2G6 mutations." (PMID 20886109, 2010). "Here, we describe the clinical features of several PLA2G6-associated neurodegenerative diseases." (PMID 30619057, 2018). "Moreover, missense mutations in the Phospholipase A2 Group VI (PLA2G6) gene are causative to multiple neurodegenerative diseases, including INAD (infantile neuroaxonal dystrophy), NBIA (idiopathic neurodegeneration associated with brain iron accumulation) and PD14." (PMID 38962715, 2024). "At present, the pathogenesis of the PLA2G6 mutation in neurodegenerative diseases remains unclear." (PMID 30619057, 2018). "PLAN is linked to PLA2G6 mutations and belongs to NBIA, a heterogeneous group of neurodegenerative diseases characterized by iron accumulation in the basal ganglia and substantia nigra due to various disrupted cellular mechanisms." (PMID 36247768, 2022). "However, the pathogenesis of PLA2G6 in neurodegenerative diseases remains unclear and the function of iPLA2β, resulting from different mutation sites and types, may be the vital factor." (PMID 30619057, 2018). "Given that the antioxidant system is decreased in neurodegenerative diseases, we also examined the effect of α-LA on several antioxidant proteins such as GPX4, SOD or PLA2G6 in PKAN fibroblasts." (PMID 37046296, 2023).
tumor (25 papers, 2013 to 2025). "The tumor growth of PLA2G6 deficiency group was slower than that of control group." (PMID 35340268, 2022). "By the end of the experiment, the tumor weight of PLA2G6 deficiency group was notably reduced." (PMID 35340268, 2022). "In biological experiments, AURKA, BID, and PLA2G6 functioned as tumor promoters by enhancing the proliferation and migration of ccRCC cells." (PMID 40271062, 2025). "According to GEPIA, iPLA2β/PLA2G6 expression is downregulated in 15 tumor types, whereas iPLA2δ/PNPLA6 expression is only downregulated in three types." (PMID 36765904, 2023). "For example, in radiation‐induced dying tumour cells, cleaved caspase‐3 activates phospholipase A2 group VI (iPLA‐2) to enhance prostaglandin E2 (PGE2) secretion, which subsequently promotes the proliferation and growth of surviving tumour cells." (PMID 36639835, 2023). "Through CCK8 and colony formation assays in vitro and xenograft tumor experiment in vivo, we found that knockdown of PLA2G6 dramatically inhibited cell proliferation." (PMID 35340268, 2022). "Several studies illustrated that PLA2G6 was involved in proliferation, metastasis, and apoptosis in tumor cells." (PMID 35340268, 2022). "We further detected the effect of PLA2G6 knockdown on tumor xenograft growth in the BALB/c nude mice injected with M14 cells." (PMID 35340268, 2022). "PLA2G6 was involved in multiple malignant behaviors in tumor cells, including proliferation, metastasis, and apoptosis." (PMID 35340268, 2022). "Our findings revealed that EZH2, AURKA, BID, PLA2G6, and EPAS1 exhibited significantly elevated expression levels in ccRCC tumor tissues compared to normal tissues." (PMID 40271062, 2025). "Several immune-related genes were shared across tumor types, with seven genes (CASP3, F2RL1, CD22, RORC, PLA2G6, SYCP1, MAP3K5) common to all four histologies." (PMID 40621458, 2025). "Although knockdown of PLA2G6 showed no obvious effect in both bulk tumor cells and TRCs, PLA2G6 was upregulated approximately three-fold in TRCs." (PMID 38720107, 2024). "The rest genes, CD46, CXCL6, GPI, ITGB1, PLA2G6 and TNFSF4, were revealed for the negative association with tumor suppression." (PMID 35832540, 2022).
cancer (19 papers, 2009 to 2025). A tumor composed of atypical neoplastic, often pleomorphic cells that invade other tissues. "Considering the pivotal role of inflammation in cancer, understanding the underlying molecular mechanisms of iPLA2, phospholipase A2 group VI (PLA2G6) in AAM pathway-mediated tumorigenesis is imperative." (PMID 35011685, 2021). "For this reason, it can be thought that decreased iPLA2β/PLA2G6 expression may be a hallmark of cancer." (PMID 36765904, 2023). "The expression of PLA2G6 from the online databases found that PLA2G6 is overexpressed in many human cancers." (PMID 35340268, 2022).
neurological disorders (8 papers, 2013 to 2024). "Yet, it is still consistent with the complex nature of PLA2G6‐associated phenotypes and its tendency to feature multiple neurological disorders despite the rarity of its mutations." (PMID 37139542, 2023). "Indeed, loss of function of both PCYT2 and PLA2G6 leads to severe neurological disorders, with biallelic mutations in PCYT2 causing a complex form of HSP with optic nerve atrophy, which is associated with neutral ether lipid and ether phospholipid abnormalities." (PMID 37463447, 2023). "Research on PLA2G6 has predominantly focused on neurological diseases, and its relationship with androgen levels and fat deposition remains unexplored." (PMID 39123669, 2024).
metabolic disease (3 papers, 2024 to 2026). A congenital disorder (due to inherited enzyme abnormality) or acquired (due to failure of a metabolically important organ) disorder resulting from an abnormal metabolic process. "Phospholipase A2 group VI (PLA2G6, also called iPLA2β) has been implicated in male fertility, neuronal disorders, and metabolic diseases." (PMID 42007880, 2026). "Key genes, including PLA2G12A, PLA2G6, and TNFAIP8, offer potential therapeutic targets for metabolic diseases." (PMID 39277575, 2024).
movement disorder (3 papers, 2024 to 2025). Neurological conditions resulting in abnormal voluntary or involuntary movement, which may impact the speed, fluency, quality and ease of movement. "To model movement disorders connected with PLA2G6-associated neurodegeneration, we used the well-established climbing assay." (PMID 41404033, 2025). "Thus, while PLA2G6 loss of function clearly causes movement disorders, it is less clear whether specific subsets of neurons are more vulnerable than others." (PMID 41404033, 2025). "Comparative Genomic Hybridization (CGH)-array and gene testing for mutations in PLA2G6, PANK2 and SPG7 were negative, as well as NGS-based panel screening of 102 genes associated with movement disorders in childhood." (PMID 39063023, 2024).
neurodevelopmental disorder (2 papers, 2025 to 2026). A behavioral and cognitive disorder with onset during the developmental period that involves impaired or aberrant development of intellectual, motor, or social functions. "In case 10, in addition to the compound heterozygous PLA2G6 variants already reported after ultrarapid LR-GS, standard genomic care identified a heterozygous pathogenic variant in IRF2BPL (Neurodevelopmental disorder with regression, abnormal movements, loss of speech, and seizures; MIM#618088)." (PMID 41116046, 2026).
immune disorders (1 paper, 2022). "Even though immune disorders are rare among patients with PLAN, the protein encoded by PLA2G6 plays a role in inflammation and immune responses, and PLA2G6 knockout mice also show evidence of neuroinflammation." (PMID 35624904, 2022).
mental illness (1 paper, 2023). "We screened our whole exome sequencing data of familial severe mental illness families for PLA2G6 variants." (PMID 38028602, 2023).
PLA2G6 also shares sentences with these, for which no sentence is quoted: infection (5 papers); Cerebellar ataxia (3); depression (3); Dyskinesia (3); glioma (3); hepatocellular carcinoma (3); ischemic stroke (3); cardiovascular disease (2); Cerebral ischemia (2); dementia with Lewy bodies (2); hereditary ataxia (2); Spastic paraplegia (2); adenocarcinoma (1); Adult onset (1); Anxiety (1); Arrhythmia (1); atherosclerosis (1); autosomal dominant mental retardation type 35 (1); bacterial infection (1); basophilic leukemia (1); bladder cancer (1); brain iron accumulation (1); breast tumors (1); bronchopulmonary dysplasia (1); cardiac hypertrophy (1); carnitine deficiency (1); cerebellar degeneration (1); cerebral infarction (1); Chagas disease (1); Coffin-Lowry syndrome (1).
A further 51 diseases each share a sentence with PLA2G6 in 1 paper.